HNF4A (hepatocyte nuclear factor 4 alpha)
Diseases named in the same sentence as HNF4A in open-access papers (continued):
Sharing a sentence is not in itself a finding about the gene and the disease.
cancer (continued). "PARP-1, a protein involved in the response to single and double strand DNA breaks and important to many cancers, was confirmed for interaction after pulldown of the endogenous HNF4α from both HT-29 and LoVo cells." (PMID 31060309, 2019). "An identical trend was observed in a different data set, with highest expression in cancer being observed for genes activated by both HNF4A and GATA6." (PMID 30962179, 2019). "In cancer cells, inhibition of HNF4α leads to an inflammatory-response-mediated regulatory feedback loop initiating and maintaining hepatocellular carcinogenesis via STAT3-mediated induction of miR-24 and miR-629 expression." (PMID 31557902, 2019). "To further confirm the cellular effects of HNF4α and E47 activation, we detected expressions of other genes related to the differentiation of the two cancer cells." (PMID 30973327, 2019). "The three most frequently gained loci in the whole data set were HNF4A in 803 or 47% of 1699 cancers, KLF5 (709 or 42%) and MYC (585 or 34%), all of which have previously been implicated as amplification targets in CRC8,13,14." (PMID 30202008, 2018). "Expression profile of its isoforms has been demonstrated modified in many cancers including CRC, and it was implicated that the interaction between Src tyrosine kinase and HNF4α has important implications for colon and other cancers." (PMID 29547645, 2018). "RNA microarray and gene functional analysis revealed that suppressing HNF4α not only impaired many biosynthesis and metabolism pathways of hepatocytes but also increased pathways for cancer." (PMID 28807057, 2017). "Persistence of the circuit results in prolonged activation of HNF4α, uncontrolled cell proliferation, and, eventually, cancer progression." (PMID 26870992, 2016). "Of course, controversy about the powers of HNF4α in regard to cancer challenges the belief that HNF4α promotes cancer-induction." (PMID 26870992, 2016). "We observed that bile ducts located within undifferentiated carcinoma showed weak expression of HNF4α, which is in line with previous studies describing HNF4α expression in activated bile ducts." (PMID 27323406, 2016). "In line with that, the number of HNF-4α positive cells in BKS.Cg db/db mice has doubled during cancer development from week 11 (pre-cancer stage) to week 19, while remaining essentially constant in fat-1 mice." (PMID 25375205, 2014). "Given its use as an anti-diabtetogenic and hypolipidemic agent, we treated D283MED cells with MEDICA 16 based on the position of HNF4A at a hub of direct and indirect relationships with critical molecules in transcription/translation and cancer biology." (PMID 22848702, 2012). "In other carcinomas, deregulation of HNF4α leads to increased cellular proliferation, progression and dedifferentiation." (PMID 22629454, 2012). "A gene profiling analysis in diseased Hnf4α null colon confirms profound genetic changes in cell death and proliferative behaviour related to cancer." (PMID 19898610, 2009). "HNF4α was identified as a key factor associated with EMT and stemness linked to the Wnt/β-catenin pathway, metabolic regulation via NOTCH signaling, YAP/Hippo pathway, cell cycle modulation, and reactive oxygen species system in cancers." (PMID 40277924, 2025). "Further study found that BBR could reduce the expression of HNF4α, WNT5A, and cytoplasmic β-catenin in cancer tissues, and the regulation of HNF4α-Wnt5a is a crosstalk between AMPK metabolic pathway and WNT signaling pathway." (PMID 40092702, 2025). "Targeting HNF4α through selective agonists or modulators presents a promising strategy to restore its function in metabolic diseases and provide targeted treatments for specific cancer subtypes." (PMID 40926269, 2025).
cancer (continued). "Its suppression by insulin via downregulation of HNF4α links hepatic metabolic status to systemic hormonal control, establishing SHBG as a key mediator at the intersection of metabolic dysfunction, hyperinsulinaemia, and cancer risk." (PMID 41586225, 2025). "HNF4α was identified as a novel biomarker and a promising target for cancer therapy." (PMID 40277924, 2025). "In contrast, CDH1, encoding for E cadherin, showed a higher mutation rate in ELF3/HNF4A non-up-regulated cancers (16.7% vs. 6.1% in the up-regulated group), which was not however statistically significant (Student’s t-test p = 0.17)." (PMID 41425714, 2025). "Second, we integrated the HNF4A cancer-specific methylation with expression data." (PMID 39165427, 2024). "Hepatocyte nuclear factor 4 alpha (HNF4α) is the most abundant DNA-binding protein in liver and binds to DNA as a homodimer to regulate expression of genes in lipid metabolism; aberrant expression of HNF4α is a prominent feature in many diseases including cancer." (PMID 39199690, 2024). "Additionally, to evaluate the effect of HNF4A on the stemness of the spheroids, we screened for expression of cancer stem cell markers, including CD24, CD44, NESTIN, OCT4, and SOX2." (PMID 39165427, 2024). "Furthermore, RT-pPCR analysis of normal and cancer pancreatic tissues showed that both P1 and P2 HNF4A isoforms are suppressed in cancer (Figure A13)." (PMID 39165427, 2024). "HNF4α plays a key role in the modulation of NF-κB signaling during cancer development." (PMID 38372868, 2024). "HNF4A displayed cancer-specific hypermethylation in the promoter and gene body regions." (PMID 39165427, 2024). "Converging lines of evidence implicate HNF4A in the development of several kinds of cancer." (PMID 39399686, 2024). "As HNF4A acts as a selective agonist of the peroxisome proliferator-activated receptor gamma (PPARγ), our analyses suggest its potential as a novel biomarker and target for cancer prevention." (PMID 38645221, 2024). "The HNF4α protein has been suggested as a prominent drug target in metabolic disorders and cancers." (PMID 37732120, 2023). "On the other side, HNF4A also plays antitumor roles in several types of cancer." (PMID 35132353, 2022). "On the one side, HNF4A could serve as a cancer promoter by facilitating the proliferation and invasion of cancer cells." (PMID 35132353, 2022). "Recently, HNF4α has been emerging as a key player in a variety of cancers." (PMID 36249028, 2022). "On the other hand, several genes downregulated in the HNF4A gene network are involved in lipid and cholesterol metabolism, and the downregulation of these genes may promote cancer development." (PMID 35327967, 2022). "Thus, several strategies have been employed to induce HNF4a overexpression in cancer cells using long-non coding RNAs, premade DNA vectors for HNF4a, miRNAs, small molecules, recombinant proteins, and growth factors." (PMID 36132168, 2022). "We need to explore the function of HNF4a as a circadian clock gene in malignant tumors further." (PMID 33628089, 2021). "Herein, we discuss emerging insights into the roles of HNF4α in several types of cancer." (PMID 33462379, 2021). "While investigations into therapeutic methods based on HNF4α are currently in early stages, more therapeutic achievements could be attained in the future with an increased understanding of the mechanisms and functions of HNF4α in cancer." (PMID 33462379, 2021). "Moreover, HNF4A was also reported to be a potential biomarker in several cancers, such as breast cancer, liver cancer and colon cancer." (PMID 34309216, 2021). "Thus, the double-negative feedback loop formed between Wnt/β-catenin signaling and HNF4α is involved in the regulation of cancer progression." (PMID 33462379, 2021). "As expected, HNF4α is involved in the regulation of NF-κB signaling in cancer progression." (PMID 33462379, 2021).
cancer (continued). "Although there is an abundance of evidence indicating that HNF4α plays an important role in embryonic development and controlling biological functions, its role in the regulation of tumorigenesis and cancer development remains unclear." (PMID 33462379, 2021). "Further investigations are needed, but drugs that target HNF4α could be valuable in combination cancer treatments." (PMID 33462379, 2021). "We examined additionally whether GATA3 or Hnf4a affects the malignant features and tumorigenicity of cancer cells." (PMID 34595169, 2021). "Moreover, HNF4α can cause dysregulation of miR-122 to promote the induction of c-Met and activate the phosphorylation of STAT3, contributing to cancer aggressiveness." (PMID 33462379, 2021). "Expectedly, HNF4α suppression has been reported in cancers, including HCC." (PMID 32023898, 2020). "High expression of HNF4A leads to decreased growth of cancer cells." (PMID 32093682, 2020). "Knockdown of either ASGR or HNF4A reversed OF mediated anti‐cancer cell proliferation." (PMID 33377648, 2020). "These conflicting reports implicate that HNF4α may perform different roles in different cancer types or stages of cancer development." (PMID 31695151, 2020). "HNF4α and E47 are used to differentiate liver and panaceas cancer cells into normal cells." (PMID 30973327, 2019). "Recent work supported that P2 isoform classes of HNF4α promote cancer cell survival." (PMID 31060309, 2019). "The HNF4α expression is altered in cancers of all the tissues where it is expressed." (PMID 31060309, 2019). "HNF4α has been reported to affect cell proliferation and chemoresistance in several cancers." (PMID 30867652, 2019). "Because prior studies have revealed that MYC can repress BMAL1 expression in specific cancer cells, we co-transfected the cells with siMyc or scrambled oligonucleotides to determine the extent to which HNF4α repression of Bmal1could be indirect through changes in Myc expression." (PMID 30341289, 2018). "Ectopic expression of BMAL1 in HepG2 cells resulted in a transient loss of HNF4α expression; and cancer cells, but not AML12 cells overexpressing BMAL1, showed reduced proliferative capacity over 48 h." (PMID 30341289, 2018). "Among the top 10 enrichment scores, suppressing HNF4α cells greatly reduced the pathways of biosynthesis (steroid, terpenoid backbone, aldosterone, unsaturated fatty acids) and biometabolism (fatty acid, carbon), while increasing pathways in cancer, compared to HNF4α-overexpressing cells." (PMID 28807057, 2017). "Considering c-Myc as an essential transformation marker of aggressive carcinoma cells, the less migratory hepatocytes derived from HNF4α-overexpressing progenitors in vivo reduce the maltransformation possibility of the transplanted cells and provide expandable cells for transplantation." (PMID 28807057, 2017). "On the other hand, replication of cancer-initiating virus HBV is dependent on expression of HNF4α." (PMID 26870992, 2016). "Interestingly, two distinct promoters (HNF4A-P1 and HNF4A-P2) are known to increase the expression of HNF4A in some cancers." (PMID 27016420, 2016). "The most significant network associated with these genes was related to cancer (IPA score = 51), followed by a network associated with DNA replication, recombination and repair (IPA score = 36) that contained a HNF4A module." (PMID 23423481, 2013). "The clear disease involvements shown for HNF4α suggest that modulating its expression levels or its protein function by drug-like molecules could be promising for control of metabolic disorders or cancer." (PMID 37732120, 2023). "Similarly, the role of different HNF4α isoforms in cancer is worthy of further study." (PMID 33462379, 2021). "Indeed, a synthetic HNF4A antagonist is under investigation to selectively eradicate cancer cells." (PMID 32357464, 2020).
cancer (continued). "Across all cancer cell lines, we observed that many more genes were depleted rather than enriched in these screens, with DPH5, ZNF124, ABL1, and HNF4A showing the most significant toxicity." (PMID 39870664, 2025). "HNF4α has emerged as a potential candidate for CRAC therapy, in view of its elevated expression levels across various types of cancer." (PMID 40277924, 2025). "Immunohistochemistry (IHC) analysis of FOXA1, HNF4A and HNF4G from primary PDAC tissue samples confirmed coexpression of these transcription factors, only in the cancer epithelial cells." (PMID 41168397, 2025). "Conversely, HNF4α exhibits oncogenic behavior in HCC and plays a role in cancer development and metastatic tumor formation." (PMID 40277924, 2025). "When HNF4α protein expression was compared among various cancers using the HPA004712 antibody, the highest expression of HNF4α was observed in CRAC tissue samples relative to the other types of solid cancers, including STAD and PAAD." (PMID 40277924, 2025). "As these mutations are associated with treatment resistance, their presence may counteract the lower risk clinicopathologic features associated with ELF3/HNF4A up-regulated cancers and could explain the lack of statistically significant differences in survival outcomes." (PMID 41425714, 2025). "NRs such as AR, estrogen receptor (ER), farnesoid X receptor (FXR), glucocorticoid receptor (GR), hepatocyte nuclear factor 4 alpha (HNF4α), liver X receptors (LXR), PPARs and pregnane X receptor (PXR) function as regulators of both inflammation and cancer." (PMID 39199690, 2024). "In precancers, HNF4A decreases to drive WNT signaling, while in carcinomas, it is upregulated in CSCs to drive malignancy." (PMID 38645221, 2024). "In most cancers, GPX2, HNF4A, and STMN1 were hypomethylated, while the majority of cancer genes exhibited hypermethylation." (PMID 37304867, 2023). "These cancers fall into the 2 main subtypes as before, with clear differential expression of the lineage factors GATA6 and HNF4A." (PMID 35536676, 2022). "In our analysis, both HNF4A and HNF4A.1 were identified as top-ranked motifs for the DIAD class, of which all the three cancer types originated in organs of the gastrointestinal tract (i.e., the esophagus, stomach, and large intestine)." (PMID 35227282, 2022). "Increasing studies have demonstrated that HNF4A, FOSL2, and GATA4 showed aberrant expression in various malignant tumors, playing a role in promoting or inhibiting malignancies, and our study results were consistent with these studies." (PMID 33588380, 2021). "In vitro cell line studies demonstrated that HNF4α promoted proliferation and gemcitabine resistance to PDAC cancer cell lines." (PMID 30867652, 2019). "It has been reported that the cancer cells HepG2 and PANC1 can be differentiated into normal liver- and pancreas-like cells by exogenously expressing transcription factor HNF4α and E47." (PMID 30973327, 2019). "As for this, 114 cases of RCC samples were collected to detect the expression of VHL, HNF-4α and ALDH2 in cancer and adjacent tissues by immunohistochemical assay." (PMID 28643803, 2017).
cancer (continued). "Lower mRNA expression of VHL, HNF-4α and ALDH2 were found in cancer tissues compared to their corresponding adjacent tissues, and there was a positive correlation between VHL and HNF-4α mRNA and between HNF-4α and ALDH2 mRNA." (PMID 28643803, 2017). "Significantly lower expression of VHL, HNF-4α and ALDH2 were found in cancer tissues than their corresponding adjacent tissues." (PMID 28643803, 2017). "In the present work, we aimed to evaluate HNF4A together with the expression of ER, PR, and GCDFP-15 to investigate the discrimination of cancers in 126 Brazilian patients." (PMID 28583188, 2017). "Therefore, it will be important to keep the HNF4α-Alu elements in mind when investigating HNF4α function, especially when using non primates as models for humans and when investigating conditions, such as cancer, where there may be genome-scale alterations in chromatin accessibility." (PMID 22085832, 2011). "The variable expression of HNF4α over different stages of cancer progression highlights the significant challenges in developing targeted therapies for CRAC and suggests that HNF4α-targeting strategies may only benefit a specific subset of CRAC patients." (PMID 40277924, 2025). "Hepatocyte nuclear factor 4 alpha (HNF4α) transcriptionally activates brain cytoplasmic RNA 200 (BC200), which in turn serves as a molecular scaffold, enhancing FMRP's ability to bind to and regulate key cancer-related mRNAs, including that of HNF4α itself." (PMID 40271197, 2025). "Accordingly, we hypothesized that a low-HNF4α state of CRAC could contribute to the suppression of inflammatory NF-κb signaling and activation of the YAP/Hippo pathway for cancer progression and dedifferentiation." (PMID 40277924, 2025). "After 2 weeks, mice developed carcinomas resembling HCC with the expression of hepatocyte nuclear factor-4α (HNF4α) that lacked glandular structures and keratin 19 (KRT19) expression typical for CCAs." (PMID 39948437, 2025). "In contrast, cancers with low CDX2 showed higher SOX2 expression (mean expression z-score relative to all samples = 0.42, Student’s t test p < 0.0001) and significant HNF4A suppression (mean expression z-score relative to all samples = −1.07, Student’s t test p < 0.0001)." (PMID 39768557, 2024). "We found that HNF4A and HNF4G were completely absent from cancer cells, whereas normal adjacent epithelial cells maintained nuclear HNF4A and HNF4G staining." (PMID 37309673, 2023). "HNF4α plays a pivotal role in the maintenance of epithelial/hepatocyte phenotype and regulates dynamic events of EMT by suppressing snail, the master regulator of EMT, and increasing E-cadherin in cancer cells." (PMID 36132168, 2022). "Notably, the RNA-Seq data obtained from The Cancer Genome Atlas (TCGA) database of cancer patients showed that the expression of HNF4A and HNF1A mRNA is significantly correlated in many cancer types." (PMID 35327967, 2022). "This chromatin remodelling revealed that the HNF4A and PPARGC1A regulated transcriptional regulatory networks play a pivotal role in promoting the emergence of drug resistant cancer cells and represent potential therapeutic targets to enhance the efficacy of ERBB2 inhibition strategies." (PMID 36153371, 2022). "Since SOX9+/HNF4α+ HybHPs was regenerated in the injured liver without developing into cancer, we focused on the Hoxb6 effects on the HybHPs." (PMID 32763157, 2020).